PLK1 (polo like kinase 1)
Diseases named in the same sentence as PLK1 in open-access papers (continued):
Sharing a sentence is not in itself a finding about the gene and the disease.
cancer (continued). "Other studies showed that PLK1 down-regulation sensitizes cancer cells to chemotherapy and can revert chemoresistance." (PMID 26085038, 2015). "One attractive target gene in the fields of signaling research and cancer therapy is the serine/threonine kinase Plk1 (polo-like kinase 1), which shows elevated activity in all human tumors." (PMID 26317649, 2015). "Based on strong preclinical data for PLK1 inhibition and decreased cancer cell growth, several PLK1 chemical inhibitors are in clinical trial." (PMID 25557168, 2015). "Polo-like kinase 1 (PLK1) is highly expressed in many cancers and therefore a biomarker of transformation and potential target for the development of cancer-specific small molecule drugs." (PMID 25574601, 2015). "FOXM1 overexpression has been observed in a variety of different tumour types and our recent work indicated that in the context of OAC, several of its target genes, including PLK1, are co-ordinately overexpressed in this cancer type." (PMID 25889361, 2015). "Several studies have also demonstrated a role for PLK1 in promoting the growth and survival of cancer stem cells." (PMID 25557168, 2015). "In this study, we used NPC as a model to investigate the specific sensitivity of cancer cells to targeting PLK1 and Aurora kinases." (PMID 25871386, 2015). "Here, the detailed understanding of how mitotic kinases such as polo-like kinase (Plk) 1 orchestrate mitosis, built over the years in basic academic research, inspired the industry to consider Plk1 inhibition as a potential therapeutic cancer target." (PMID 25422355, 2015). "siRNA-mediated silencing of PLK1 in several cancer cell lines was shown to result in decreased cell viability with induction of apoptosis, defects in several mitosis processes and G2/M phase arrest." (PMID 26085038, 2015). "The overexpression of PLK-1 is strongly correlated with a wide spectrum of human cancers and poor prognosis." (PMID 26557691, 2015). "PLK1 inhibitors are currently being developed for cancer therapy and it is likely that cells demonstrating coordinated up regulation of FOXM1 and PLK1 expression will be particularly susceptible to such treatment." (PMID 26576650, 2015). "Plk1 plays a pivotal role for mitosis and as a measure for the aggressiveness of a tumor due to its important role for the mitotic checkpoints of cancer cells." (PMID 26317649, 2015). "Polo-like kinase 1 (PLK1) is a serine-threonine protein kinase which is overexpressed in cancer cells, and plays a major role in regulating tumor growth." (PMID 25557168, 2015). "PLK1, the best-characterized mammalian PLK, is a particularly attractive target for cancer drug development because most cancers require its activity." (PMID 25574601, 2015). "It is of importance to identify biomarkers, which contribute to the cytotoxicity of Plk1 inhibitors and help to select suitable cancer patients for this molecular intervention." (PMID 25483104, 2015). "PLK1 expression is increased in several types of cancers including urothelial carcinoma of bladder, renal cancer, breast cancer, prostate cancer, neuroblastoma, hepatocellular carcinoma, cervical carcinoma, and non-melanoma skin cancers." (PMID 25574601, 2015). "The second target gene, which attracts increasing attention in the fields of signaling research and cancer therapy, is the serine/threonine kinase Plk1 (polo-like kinase 1), because it shows elevated activity in all human tumors." (PMID 24810255, 2014). "For example, in cancer cells with a KRAS gene mutation, the inhibition of polo-like kinase 1 (PLK1) resulted in cell death." (PMID 24378760, 2014). "We demonstrate for the first time that cellular senescence is the predominant outcome of Plk1 inhibition in some cancer cell lines, whereas in other cancer cell lines the dominant outcome appears to be apoptosis, as has been reported in the literature." (PMID 25365521, 2014).
cancer (continued). "Depletion or inhibition of Plk1 in cancer cells leads to mitotic arrest and subsequent apoptotic cell death." (PMID 25036740, 2014). "SBE13 is a selective type II Plk1 inhibitor which is able to induce a delay in cell cycle progression, to reduce cell proliferation and to induce apoptosis in a broad range of human cancer cell lines." (PMID 24810255, 2014). "Plk1 is overexpressed in many types of human cancers and plays a critical role in cellular proliferation from yeast to mammals." (PMID 25036740, 2014). "Because the overexpression of Plk1 is strongly correlated with the aggressiveness and prognosis of several cancers, Plk1 has been examined as a potential target for specific inhibitory drugs in anti-cancer therapy." (PMID 25211362, 2014). "Since Plk1 is highly expressed in proliferating cells, including many cancer cells, it has already been intensely validated as an anti-cancer drug target, and several inhibitors that specifically inhibit Plk1 activity are available." (PMID 24901228, 2014). "SBE13 displayed a differential effect between cancer and primary cells, confirming earlier studies using Plk1-specific siRNAs." (PMID 24810255, 2014). "The importance of Plk1 as a measure for the aggressiveness of a tumor results from its important role for the mitotic checkpoints of cancer cells." (PMID 24810255, 2014). "This study is the first to report the induction of senescence in response to Plk1 inhibition both in vitro and in vivo, particularly in cancer cells." (PMID 25365521, 2014). "These processes depend on the activities of Aurora A kinase and its downstream target Plk1, which has prompted interest in their function as anti-cancer targets." (PMID 25268741, 2014). "This activity was significantly suppressed in presence of BI 2536, a Plk1 inhibitor that has been tested in clinical trials against cancer." (PMID 24901228, 2014). "Plk1 plays a pivotal role for mitosis especially of cancer cells and thus as a measure for the aggressiveness of a tumor." (PMID 24810255, 2014). "In this work, we present the in vitro and in vivo consequences of Plk1 inhibition in cancer cells using potent, selective small-molecule Plk1 inhibitors and Plk1 genetic knock-down approaches." (PMID 25365521, 2014). "Recent studies have shown that miR-143, miR-100, miR-593* and miR-10b* target the Plk1 expression in cancer cells." (PMID 23948487, 2013). "Among the multiple roles of PLK1 in cell division, kinase activity has emerged as an attractive target in anti-proliferative cancer therapy." (PMID 24349352, 2013). "Here, in an effort to identify Plk1-based novel PTM targets involved in cancer phenotype and cell-cycle progression, we have merged in silico sequence and structure-based approaches." (PMID 23967120, 2013). "Excitingly, clinical and pre-clinical studies have suggested Plk1, Aurora A and Wip1 as promising drug targets to confer enhanced cancer therapy, consistent with the role of these kinases in checkpoint recovery, mitosis, and other processes." (PMID 23618492, 2013). "Plk1 plays a key role to ensure the normal mitosis and is mainly expressed in proliferating tissues but overexpressed in cancers." (PMID 24216699, 2013). "It has been widely proposed that Plk1 depletion/inhibition preferentially kills cancer cells compared with normal cells." (PMID 23948487, 2013). "All cloned promoters were shown to be substantially more activein cancer cells than in fibroblasts, while the PLK1 promoter was the mostcancer-specific and promising one." (PMID 24303203, 2013).
cancer (continued). "Plk1 is overexpressed in a broad spectrum of human cancers, and elevated Plk1 activity is thought to promote tumorigenesis, while Plk2 and Plk3 play key roles in genetic stability and preventing oncogenic transformation." (PMID 24223211, 2013). "Up-regulation of human Polo-like kinase (Plk1) is prevalent in many human cancers, and identifying potent inhibitors of Plk1 is the focus of much research." (PMID 24019759, 2013). "PLK1 has been recognized as a promising target for cancer therapy for its essential role in mitosis." (PMID 24025726, 2013). "One of the target proteins in cancer therapy is serine/threonine-protein kinase (PLK1), a key regulator of mitosis in mammalian cells." (PMID 24159333, 2013). "Significantly, Plk1 is over-expressed in many human cancers, including liver cancer, and this up-regulation correlates with poor cancer prognosis." (PMID 23507839, 2013). "For example, cyclin-dependent kinase 1 (CDK1), polo-like kinase 1 (PLK1), and cancer susceptibility candidate 5 (CASC5) took part in the regulating proliferation of CAF itself and tumor cell." (PMID 23577100, 2013). "Polo-like kinase 1 (PLK1), which is upregulated in many cancers, plays a pivotal role in all phases of mitosis." (PMID 24381593, 2013). "The inhibition of PLK1 results in cell apoptosis, and it has been validated as a target for cancer therapy." (PMID 24205328, 2013). "Polo-like kinase 1 (PLK1), one of the key regulators of mitosis, is a target for cancer therapy due to its abnormally high activity in several tumors." (PMID 23658603, 2013). "So far, some PLK1 inhibitors have demonstrated encouraging results in phase 1 or 2 clinical trials of cancer treatment." (PMID 24025726, 2013). "Due to an ensemble of interconnecting functions of Plk1 in cell-cycle process and various carcinomas, the urge to describe intricate detail of novel PBD binding targets in conjunction with kinase association is overwhelming." (PMID 23967120, 2013). "This novel mechanism would have broad reaching implications given that PLK1 is central to the growth of many types of cancer." (PMID 23047041, 2012). "PLK1 is overexpressed in a wide variety of cancers, and inhibition of this kinase by shRNA or chemical inhibitors decreases tumor growth both in vitro and in vivo." (PMID 22390279, 2012). "Compared to normal tissues, Plk1 is overexpressed in many cancers, e.g. breast cancer, ovarian carcinoma colorectal carcinoma, uterine cancer, skin cancer, stomach cancer, and others." (PMID 23227884, 2012). "Some studies have shown that PLK1 expression is elevated in many cancers including non-small cell lung cancer, head and neck cancer, colorectal cancer, and others." (PMID 23233862, 2012). "Polo-like kinase 1 (PLK1) is highly expressed in many human cancers and regulates critical steps in mitotic progression." (PMID 23151088, 2012). "Firstly, it is over-expressed in many cancers and can serve as a biomarker to monitor treatment efficacy of Plk1 inhibitors." (PMID 23227884, 2012). "Inhibition of Plk1 by RNA interference in cancer cells in vitro resulted in mitotic arrest and subsequent apoptosis." (PMID 23227884, 2012). "RNA interference experiments in vitro and in vivo have indicated that downregulation of Plk1 expression represents an attractive concept for cancer therapy." (PMID 23227884, 2012). "PLK1 is overexpressed in a wide variety of cancers, and inhibition of this kinase preferentially kills cancer cells over normal cells." (PMID 23056340, 2012). "PLK1 gene and protein expression have been regarded as new prognostic markers for many types of malignancies, as well as a potential target for cancer therapy." (PMID 23233862, 2012). "Polo-like kinase 1 (PLK1) is highly expressed in many cancers and regulates critical steps in mitotic progression." (PMID 22390279, 2012).
cancer (continued). "PLK1 represents an exquisite prognostic marker and target for cancer therapy because of its strong expression in cancer but weak expression in normal tissues." (PMID 23227884, 2012). "Immunohistochemical investigation demonstrated that PLK1 protein was expressed weakly in cancer-adjacent tissues (0.65±0.12%)." (PMID 23226764, 2012). "DH281 and DH287 also induced formation of monopolar spindles in HeLa cells (data not shown), and this finding is consistent with the observation in cancer cells treated with a known PLK1 inhibitor BI2536 or with PLK1 RNAi." (PMID 23056340, 2012). "Of the 28 selected kinases in our focused studies, PLK1 is the leading candidate, based on its activity in inhibiting cancer cell growth, and in particular, its activity against the TICs once silenced by siRNA or by the small-molecule inhibitor, BI 2536." (PMID 22309939, 2012). "Polo-like kinase 1 (Plk1) is an interesting molecule both as a biomarker and as a target for highly specific cancer therapy for several reasons." (PMID 23227884, 2012). "Studies have shown that cancer cells display a higher dependency on Plk1 for cell proliferation and mitosis than primary cells." (PMID 22852086, 2012). "We synthesized additional 18 beta-carboline derivatives and examined the growth inhibition of several non-cancer and cancer cell lines as well as their activities against PLK1 and other kinases." (PMID 23056340, 2012). "Plk1, Aurka, Aurkb and Cdca8 are in the top 50 co-expressed genes, these play an important role in cancer formation." (PMID 23039964, 2012). "Recent evidence indicates that inhibition of PLK1 also impairs DNA replication and results in slow S-phase progression in cultured cancer cells." (PMID 23056340, 2012). "Since Plk1 is overexpressed in many cancers, it represents an interesting target molecule for the development of specific inhibitors to selectively treat cancer while avoiding toxicity towards normal tissues." (PMID 23227884, 2012). "Down-regulation of PLK1 activity has been shown to inhibit cell proliferation of cancer cell lines and tumor xenografts." (PMID 23056340, 2012). "It is likely that PLK1 is essential for cell division in cancer cells and the inhibition of PLK1 leads to a more dramatic cell cycle defect, resulting in more apoptotic cells." (PMID 23056340, 2012). "To test if these compounds inhibit the growth of cancer cell lines by targeting PLK1, we first compared the sensitivity of wild-type and cdc5-2 temperature sensitive yeast mutants to these compounds." (PMID 23056340, 2012). "Polo-like kinase 1 (Plk1) plays a critical role in cell division and represents a promising target for cancer therapy." (PMID 23227884, 2012). "Recently, Plk1 has been successfully explored as a target in cancer treatment based on its role as a mitotic inhibitor." (PMID 22701722, 2012). "PLK1 is an attractive target for cancer treatment because it plays a pivotal role in multiple steps during the cell cycle." (PMID 23056340, 2012). "It arrested various cancer cell lines with aberrant Plk1 expression in the G2/M cell cycle phase and induced apoptosis." (PMID 23227884, 2012). "PLK1 was reported to be overexpressed in a broad spectrum of cancer types, and its expression often correlates with poor patient prognosis." (PMID 22309939, 2012). "In the present review, we focus on the biology of the Plk1 enzyme and the significance of small molecule inhibitors as novel candidates for cancer therapy." (PMID 23227884, 2012). "It has been found that PLK1 is overexpressed in a variety of human tumours and has prognostic potential in cancer, indicating its involvement in carcinogenesis and its potential as a therapeutic target." (PMID 23151088, 2012).
cancer (continued). "Plk1 has received significant interest in the past few years due to its role in cell proliferation and its upregulation in many types of cancer, leading to its targeting in cancer therapies." (PMID 21253604, 2011). "Our preclinical studies demonstrated that RNAi therapy against PLK-1 using atelocollagen is effective against liver metastatic NSCLC cancers." (PMID 21884621, 2011). "Because of its role in cell proliferation, PLK1 has been proposed as a potential therapeutic target in many cancers." (PMID 21824427, 2011). "Strikingly, there is evidence thatANLN, ECT2, PRC1,RACGAP1, ASPM, and PLK1 areupregulated in a variety of human cancers and that their overexpression oftencorrelates with poor outcome (see for example and references therein)." (PMID 21386884, 2011). "In primary fibroblasts, Plk1 antibody microinjection was shown to arrest these cells with a G2-like phenotype, in contrast to the mitotic arrest in cancer cells." (PMID 20886032, 2010). "Micro-injection of Plk1 antibodies and siRNA based studies targeting Plk1 have shown the essential role of Plk1 in mitotic progression in cancer cells." (PMID 20886032, 2010). "Following prolonged mitotic arrest, cell death (apoptosis) is induced in Plk1-inhibited cancer cells and hence Plk1 has been proposed to be a promising anti-cancer target." (PMID 20886032, 2010). "The observation that PLK1 is over-expressed in human cancer has led to the development of several PLK1 inhibitors targeting the ATPase activity for cancer therapy." (PMID 20711360, 2010). "PLK1 expression has also been singled out as a biomarker of a “death-from-cancer” signature, sharing with others the function of being an activator of mitotic spindle check point proteins." (PMID 20805891, 2010). "Like in cancer cells arrested by Plk1 depletion or inhibition, we also observed cell death in primary cells following the mitotic arrest." (PMID 20886032, 2010). "BI 2536 is a new anti-mitotic drug that targets polo-like kinase 1 (Plk1) and is currently under clinical development for cancer therapy." (PMID 20886032, 2010). "It has been demonstrated that PLK-1 mRNA expression is elevated in proliferating cells, such as various cancer cell lines and tumors of different origins." (PMID 19775446, 2009). "Due to Plk1 overexpression, several Plk1 inhibitors have been developed and tested for the cancer treatment." (PMID 19161615, 2009). "PLK-1 has attracted much attention in the field of carcinogenesis and cancer therapy due to its known functions." (PMID 19775446, 2009). "Blocking PLK-1 through RNA interference has shown promise as a way to intervene in cancer progression." (PMID 19775446, 2009). "Although Plk1 is often overexpressed in human cancers, the Plk1 gene is rarely amplified, indicating that transcriptional or post-transcriptional regulation of Plk1 are affected in cancer cells." (PMID 19161615, 2009). "Mitotic kinases, in particular the Aurora family and Plk1, have generated a lot of excitement in the cancer drug discovery field." (PMID 19941817, 2009). "The G2/M phase regulator Plk1 is frequently overexpressed in cancers and correlates with aggressiveness and poor prognosis." (PMID 19216791, 2009). "Many of these studies have demonstrated that Plk1 overexpression correlates with tumor progression and patient survival rate in a variety of cancers." (PMID 19161615, 2009). "Especially, it is interesting to that PLK1 is more frequently overexpressed in papillary microcarcinoma and even in incidental carcinoma, which is smaller than 4 mm in maximal diameter." (PMID 14735186, 2004).